SLC7A11 (solute carrier family 7 member 11)
Diseases named in the same sentence as SLC7A11 in open-access papers (continued):
Sharing a sentence is not in itself a finding about the gene and the disease.
cancer (continued). "In particular, the recent discovery of disulfidptosis, a novel cell death mechanism in SLC7A11-overexpressing cancer cells, provides new insights." (PMID 40861466, 2025). "Consistent findings have been reported in other studies where inhibition of SLC7A11 triggered apoptosis in cancer cells under diverse conditions." (PMID 39354653, 2025). "Knockout experiments targeting SLC7A11 resulted in significant resistance to glucose starvation‐induced cell death in SLC7A11‐high cancer cells." (PMID 39354653, 2025). "Previous studies have identified SLC7A11 as a direct transcriptional target of p63 in cancer cells, where it supports survival under oxidative stress conditions." (PMID 40508040, 2025). "Given that both OTUB1 and SLC7A11 are upregulated in various cancers, dRib's action on this pathway suggests its potential as an anticancer agent." (PMID 41077887, 2025). "We observed that depletion of SLC7A11 partially reduced the glutamine‐dependence of the cisplatin‐resistant cancer model, supporting that up‐regulation of SLC7A11 contributes to glutamine dependency." (PMID 40784667, 2025). "As SLC7A11 is indispensable for the uptake of extracellular cystine by most cancer cells, an increase in SLC7A11 transcription upregulates cystine uptake and reduces lipid reactive oxygen species production." (PMID 41005476, 2025). "This study discovered that in glucose-deprived SLC7A11-high cancer cells, intracellular NADPH is rapidly depleted." (PMID 40303412, 2025). "Remarkably, UA enhances susceptibility to ferroptosis by impeding the SLC7A11/GSH/GPX4 Axis and suppressing the fatty acid desaturase FADS2, suggesting promising prospects for UA's clinical utility in cancer treatment." (PMID 40535804, 2025). "Investigations into cancer stemness following SLC7A11 knockout revealed marked down-regulation of the stemness marker aldehyde dehydrogenase 1 (ALDH1), alongside reductions in both the size and number of spheroids, highlighting diminished tumorigenicity." (PMID 40821110, 2025). "LINC00618 can downregulate the expression level of SLC7A11 and induce lipid peroxidation and ferroptosis in cancer cells." (PMID 40959280, 2025). "GluOC also increased GSH levels via SLC7A11 in MDA-MB-231 cancer cells, thereby preventing ferroptosis of MDA-MB-231." (PMID 40075587, 2025). "Intriguingly, thiol-reducing agents such as NAC and TCEP significantly attenuated AUR-induced cell death, mirroring their inhibitory effects on glucose starvation-induced disulfidptosis in SLC7A11-overexpressed cancer cells." (PMID 41249117, 2025). "The Cancer Genome Atlas Program (TCGA) database and immunohistochemistry validated the role of the METTL3/SLC7A11 axis in cancer progression." (PMID 39800682, 2025). "Low expression of METTL3, while high expression of SLC7A11, reduces the survival rate of cancer patients." (PMID 39800682, 2025). "SLC7A11 is frequently overexpressed in numerous human cancers, and several studies have demonstrated that SLC7A11 overexpression is directly related to the onset and progression of different types of cancer." (PMID 41438431, 2025). "The complexity of this situation highlights the potential benefits of targeting SLC7A11 in cancer therapies." (PMID 40535572, 2025). "Previous studies have demonstrated that SLC7A11 provides a survival advantage to cancer cells by inhibiting ferroptosis." (PMID 40012016, 2025). "From a metabolic perspective, cancer cells exhibiting high SLC7A11 expression (SLC7A11-high cells) import large quantities of cystine into their cytosol." (PMID 40691135, 2025). "It has been demonstrated in previous studies that SLC7A11-mediated cystine uptake in SLC7A11high cancer cells consumes substantial amounts of NADPH, making these cells highly reliant on the PPP." (PMID 40012016, 2025). "In SLC7A11-high cancer cells, SLC7A11 facilitates cystine import in exchange for glutamate export, a process critical for maintaining intracellular redox balance by promoting GSH synthesis, a key antioxidant." (PMID 40691135, 2025).
cancer (continued). "An ideal anticancer therapeutic target should meet specific selectivity for cancer growth, exert toxic killing effects in cancer cells, and have few adverse effects in normal tissue cells, and SLC7A11 appears to meet these criteria." (PMID 40855044, 2025). "Accumulating evidence has shown that METTL3 regulates ferroptosis in various cancers by modulating key factors such as SLC7A11, GPX4 and FSP1." (PMID 40175350, 2025). "Patients' data show that SLC7A11 is overexpressed in various types of human cancers, and higher levels of SLC7A11 predict poorer overall survival." (PMID 39569390, 2025). "Nevertheless, a contemporaneous study found that varying levels of SLC7A11 overexpression led to distinctly different outcomes for cancer cells." (PMID 40900810, 2025). "Taken together, our data indicate that USP10 blocks cancer ferroptosis through the transcriptional activation of SLC7A11." (PMID 40605431, 2025). "The cystine/glutamate antiporter SLC7A11 (also commonly known as xCT) is reported to mediate metabolic reprogramming in cancer by impinging on ferroptosis-dependent cell death pathways." (PMID 40332483, 2025). "For adenocarcinoma in the lung with the EGFR-mutant strain, the induction of ferroptosis halts the progression of cancer upon the administration of Vorinostat, a histone deacetylase inhibitor that mediates decreased SLC7A11 expression." (PMID 41516092, 2025). "The advancement of personalized medicine strategies that take into account the expression levels of SLC7A11 and its related pathways has the potential to improve the efficacy of cancer treatments." (PMID 40535572, 2025). "Cystine depletion from culture media or pharmacological inhibition of SLC7A11 transport using agents such as erastin or other ferroptosis-inducing compounds effectively induces ferroptosis in diverse cancer cell lines." (PMID 40821110, 2025). "Understanding the role of SLC7A11 in amino acid transport offers valuable insights into its wider implications in cancer biology and potential therapeutic strategies." (PMID 40535572, 2025). "As an important regulator of ferroptosis, SLC7A11/xCT functions to import cystine for glutathione biosynthesis and antioxidant defense, and is overexpressed in various human cancers." (PMID 40302035, 2025). "The high uptake of cystine mediated by SLC7A11 in cancer cells, coupled with glutamate export, makes SLC7A11-high cancer cells heavily reliant on glutamine and glucose." (PMID 39973065, 2025). "SLC7A11 plays a well-established role in protecting cells from oxidative stress-induced cell death, such as ferroptosis, and is overexpressed in many human cancers." (PMID 40087761, 2025). "From a metabolic perspective, disulphidptosis underscores the metabolic trade‐off that SLC7A11‐high cancer cells must contend with due to enhanced cystine uptake." (PMID 39354653, 2025). "In the preceding section, the role of SLC7A11 in promoting antioxidant activity and inhibiting ferroptosis in cancer cells was discussed." (PMID 40012016, 2025). "Recent reports have shown that ectopic expression of NSUN2 drives ferroptotic resistance in cancer cells through modulating a list of target genes, such as SLC7A11, NRF2 and GPX4." (PMID 39742570, 2025). "In cancer cells, the upregulation of SLC7A11 is often observed, which allows these cells to thrive in environments with high oxidative stress through maintaining adequate levels of cysteine for glutathione production." (PMID 40535572, 2025). "As we deepen our knowledge of SLC7A11, it is expected that new therapeutic strategies will develop, leading to more effective cancer treatments that are customized to meet the specific needs of individual patients." (PMID 40535572, 2025). "Cancer cells often maintain ROS defense even when SLC7A11 is inhibited, limiting the effectiveness of ferroptosis inducers as monotherapy." (PMID 40259468, 2025).
cancer (continued). "Among the various mechanisms governing ferroptosis sensitivity in cancer cells, the solute carrier family 7 member 11 (SLC7A11)—reduced glutathione (GSH)—GPX4 axis plays a fundamental role." (PMID 40569831, 2025). "In SLC7A11-high cancer cells, glucose deprivation leads to NADPH depletion and abnormal accumulation of disulfides, promoting disulfide bonding within actin cytoskeletal proteins." (PMID 40722814, 2025). "Inactivation of SLC7A11 or GPX4 can restore the radiosensitivity of radioresistant cancer cells and xenograft tumors." (PMID 40102409, 2025). "In previous studies, cancer treatment targeting ferroptosis has mainly been limited to solute carrier family 7a member 11 (SLC7A11) and GPX4, and currently, therapies targeting ferritinophagy receive increasing attention." (PMID 39844412, 2025). "Alongside research on disulfidptosis, these findings further elucidate the complex roles of SLC7A11 overexpression in cancer." (PMID 40900810, 2025). "RAS proto-oncogenes play a key role in promoting ferroptosis evasion in cancer cells through SLC7A11-mediated cystine uptake." (PMID 41514908, 2025). "Due to these functions, the overexpression of SLC3A2 and SLC7A11 is related to the occurrence and development of various types of cancer." (PMID 40136510, 2025). "Despite the promise of targeting SLC7A11, several challenges remain, particularly in terms of effective delivery systems to ensure selective targeting of cancer cells while minimizing off‐target effects." (PMID 41030277, 2025). "This process is particularly prominent in cancer cells with high expression of SLC7A11, especially under conditions of glucose deprivation." (PMID 40110199, 2025). "When exposed to ERS, ATF4 selectively undergoes translation to boost the expression of molecules that support the adaptive survival of cancer cells, notably SLC7A11/xCT3." (PMID 40255561, 2025). "Normally, disulfidptosis was triggered under the circumstance where glucose was deprived in high-SLC7A11-expressed cancer cells." (PMID 40083702, 2025). "Disulfidptosis is a novel type of cell death, which is triggered under the circumstance where glucose is deprived in high-SLC7A11-expressed cancer cells." (PMID 40083702, 2025). "This emerging pro‐death function of SLC7A11 reflects the elevated redox costs that SLC7A11‐high cancer cells must endure due to their heightened cystine uptake and consumption rates, rendering them susceptible to disulphide stress." (PMID 39354653, 2025). "It is plausible that SLC7A11 enhances cellular plasticity, allowing cancer cells to adaptively respond to microenvironmental cues that promote metastatic spread." (PMID 41030277, 2025). "Overexpression of SLC7A11 is closely associated with the initiation and progression of these cancers, and silencing SLC7A11 can significantly inhibit cancer cell growth and migration." (PMID 40012016, 2025). "As a result, cancer cells with high SLC7A11 expression (SLC7A11-high cells) become highly dependent on glucose to provide the NADPH required for the rapid conversion of cystine to cysteine." (PMID 40691135, 2025). "GPX4, a primary enzyme, constitutes the main surveillance system that defends against ferroptosis in cancer cells, primarily through the SLC7A11-GSH-GPX4 signaling axis." (PMID 40595451, 2025). "Disulfidptosis is driven by oxidative stress, wherein cancer cells—typically overexpressing solute carrier family 7 member 11 (SLC7A11)—enhance cystine uptake." (PMID 41049007, 2025). "In other studies, erastin and its analogs were used to downregulate SLC7A11 expression, also triggering ferroptosis in cancer cells." (PMID 40012016, 2025). "However, overexpression of SLC7A11 had also been linked to increased resistance to oxidative stress, reduced sensitivity to temozolomide, decreased endogenous ROS levels, reduced migration and invasion, changes in the actin cytoskeleton and increased cancer stem cell‐like characteristics." (PMID 39993959, 2025).
cancer (continued). "For instance, combining sorafenib with ursolic acid synergistically induces SLC7A11-dependent ferroptosis in cancer cells." (PMID 39935430, 2025). "Variant isoform of CD44 (CD44v) is an adhesion molecule expressed in cancer stem-like cells that interact with xCT and maintain SLC7A11 stability." (PMID 40249927, 2025). "Similar to our results, reduced SLC7A11 levels sensitize cancer cells to ferroptosis in different tumors." (PMID 40438588, 2025). "Many cancer cells upregulate SLC7A11 to enhance cystine uptake and augment their antioxidant capacity." (PMID 39354653, 2025). "Conversely, infusion of cystine into glucose‐starved SLC7A11‐high cancer cells rapidly reduces intracellular NADPH levels and triggers their demise." (PMID 39354653, 2025). "This dual functionality emphasizes the complexity and interconnectedness of cell death mechanisms and suggests potential therapeutic opportunities for targeting SLC7A11 in various cancers." (PMID 40535572, 2025). "Targeting SLC7A11 has the potential to disrupt the distinctive metabolic weaknesses of cancer cells, enhance the sensitivity of conventional therapies, and ameliorate the immune microenvironment, rendering it a treatment strategy with expansive promise." (PMID 40535572, 2025). "For example, in response to radiotherapy, cancer cells develop adaptive reactions, such as upregulating SLC7A11 or GPX4 expression, to fight induced ferroptosis." (PMID 40837737, 2025). "These cancer cells frequently exhibit elevated SLC7A11/xCT expression, leading to increased selenide import and a heightened demand for selenide detoxification." (PMID 39728918, 2024). "For example, in response to radiotherapy, cancer cells adapt by enhancing expressions of SLC7A11 or GPX4 to fight ferroptosis induced by radiotherapy." (PMID 38539554, 2024). "As cancer cells exhibit higher intracellular ROS content than normal cells, SLC7A11-mediated uptake of cystine is critical for the maintenance of cancer cell redox balance through the production of GSH." (PMID 39061826, 2024). "Since cancer cells exhibit strong resistance to oxidative stress, relying on the transport of extracellular cysteine, SLC7A11 is significantly upregulated in various cancer types, including ovarian cancer, hepatocellular carcinoma, and lung adenocarcinoma." (PMID 38578019, 2024). "The results indicated a close relationship between SLC7A11 and the expression of checkpoint-related genes in most cancer types, particularly PD-L1 expression." (PMID 38655266, 2024). "Numerous studies have been conducted on the function of SLC7A11 in cancer cell migration, proliferation, and chemoresistance." (PMID 39061826, 2024). "Intriguingly, IFNγ also suppresses SLC7A11-mediated cystine transport in macrophages, indicating that IFNγ can regulate SLC7A11 in both cancer and non-cancer contexts." (PMID 38322268, 2024). "Currently, numerous studies have demonstrated the widespread expression of SLC7A11 in various malignant tumors." (PMID 39807126, 2024). "SLC7A11, which is frequently upregulated in cancer, acts as a key regulatory hub within the ferroptosis pathways." (PMID 38428031, 2024). "It’s well known that SLC7A11 functions as a core modulator of ferroptosis in multiple human cancers, including TNBC." (PMID 39370446, 2024). "In contrast, SLC7A11 overexpression in cancer cells promotes glutathione biosynthesis and is insensitive to ferroptosis." (PMID 38730240, 2024). "In 2017, Gan and colleagues discovered that overexpression of SLC7A11 heightened glucose dependence in cancer cells and led to cell death when glucose was deprived." (PMID 38994937, 2024). "Most of the SLC7A11-high cancers display a strong glucose dependency and are prone resistant to ferroptosis- or apoptosis-inducing therapies." (PMID 38910181, 2024). "Elevated SLC7A11 expression introduces vulnerabilities to cancer cells, rendering them notably sensitive to glucose or glutamine deficiencies." (PMID 38317842, 2024).
cancer (continued). "Mechanistically, we found that this effect is largely dependent on the induced expression of SLC7A11, a typical inhibitor of ferroptosis, in mouse lungs human lung epithelial cells and cancer cells." (PMID 39695109, 2024). "Conversely, during glucose deprivation, cancer cells with high SLC7A11 expression undergo cystine accumulation, resulting in disulfide stress." (PMID 38685115, 2024). "This metabolic reprogramming, characterized by elevated glucose consumption, lactate production, and glutamine addiction, highlights the pivotal role of SLC7A11 as a critical ferroptosis regulator in the context of cancer metabolism." (PMID 38655266, 2024). "The specific mechanism involved circFOXP1 enhancing SLC7A11 expression in cancer cells by direct sponge adsorption of miR-520a-5p." (PMID 39309443, 2024). "These cofactors enhance the transcriptional activity of NFE2L2, thereby amplifying the expression of SLC7A11 and contributing to the inhibition of ferroptosis in cancer cells." (PMID 39534872, 2024). "SLC7A11/xCT is primarily expressed in the brain and plays functional roles in the pathophysiology of cancer and other diseases such as cardiovascular and neurodegenerative disease." (PMID 38790657, 2024). "This revelation further highlights a metabolic vulnerability of SLC7A11-high cancer cells, illuminating potential therapeutic avenues by targeting their dependence on glucose and NADPH for survival." (PMID 38428031, 2024). "In cancer cells featuring an aberrant cysteine transporter known as solute carrier family 7 member 11 (SLC7A11; also referred to as xCT), rapid cysteine uptake and conversion to cystine, in conjunction with glucose deprivation, deplete the NADPH reservoir." (PMID 38734657, 2024). "From a metabolic perspective, disulfidptosis underscores the metabolic trade-off that cancer cells with high expression of SLC7A11 (SLC7A11-high cells), have to contend with due to their elevated cystine uptake." (PMID 38428031, 2024). "SLC7A11, a key protein in regulating cancer cell metabolism, allows most cancer cells to intake cystine, reduce it to cysteine, and then use it for glutathione synthesis for antioxidation." (PMID 38491523, 2024). "Curcumin promotes the antiproliferation and ferroptosis of the colon and lung cancer cells by downregulating ferroptosis-inhibiting genes (SLC7A11 and GPX4)." (PMID 38892270, 2024). "Cancer cells with high levels of solute carrier family 7 member 11 (SLC7A11) undergo disulfidptosis, a thiol-dependent cell death induced by disulfide stress." (PMID 39737174, 2024). "Immunotherapy and radiotherapy, which are commonly used to treat cancer, can partially trigger ferroptosis by modifying the expression of SLC7A11." (PMID 38994627, 2024). "Liu’s research revealed that cancer cells overexpressing SLC7A11 undergo a unique form of cell death when exposed to glucose deprivation, distinct from recognized cell death subtypes." (PMID 38409243, 2024). "Cancer cells show increased expression of various cell surface amino acid transporters, including the Solute Carrier Family 7 Member 11 (SLC7A11)." (PMID 38790657, 2024). "As an important regulator of ferroptosis, the cystine/glutamate antiporter SLC7A11/xCT functions to import cystine for glutathione biosynthesis and antioxidant defense and is overexpressed in multiple human cancers." (PMID 38470932, 2024). "The stimulation of the HIF-1α/SLC7A11 pathway decreased HYSA’s anti-cancer activities in MG63 cells." (PMID 38686047, 2024).